MERTK (MER proto-oncogene, tyrosine kinase)
Diseases named in the same sentence as MERTK in open-access papers (continued):
Sharing a sentence is not in itself a finding about the gene and the disease.
retinal degeneration (34 papers, 2012 to 2024). Degeneration of the retina. "Caspase mediated apoptosis and MerTK-dependent phagocytosis are the underlying mechanism of photoreceptor cell death in retinal degeneration." (PMID 36650547, 2023). "MERTK was identified as the causal gene in the Royal College of Surgeons (RCS) rat model of recessively inherited retinal degeneration." (PMID 34973110, 2022). "Altogether, these results indicate that lack of galectin-3 causes excessive activation of Müller glia prior to microglia activation and leads to more severe retinal degeneration due to MERTK deficiency." (PMID 35711472, 2022). "We wondered if galectin-3 was relevant specifically for inherited retinal degeneration due to MERTK deficiency." (PMID 35711472, 2022). "Clearly, it is important to explore more effective therapies to rescue retinal function and morphology in individuals with MERTK-associated RP, especially after the initiation of retinal degeneration." (PMID 34970569, 2021). "RCS rats with inherited retinal degeneration caused by a deletion in the MERTK gene were used to evaluate the protective effect of the combination strategy." (PMID 34970569, 2021). "The mutation causing retinal degeneration in the RCS rat is in merTK, a critical tyrosine kinase involved in engulfment of both rods and cone outer segments by the RPE." (PMID 33536874, 2020). "Here, we asked if microglia activation has a primary role in the early onset of retinal degeneration due to MerTK deficiency." (PMID 32765507, 2020). "Taken together, these experiments demonstrate that early microglia inhibition is effective in delaying retinal degeneration due to MerTK deficiency." (PMID 32765507, 2020). "The Royal College of Surgeon's (RCS) rat is a well-established model of inherited retinal degeneration arising from a deletion of 409 base pairs in the gene encoding merTK." (PMID 33536874, 2020). "The MerTK-deficient mice and rats we studied exhibit early onset fast progressing retinal degeneration like human patients with mutMerTK-RP." (PMID 32765507, 2020). "More experiments are needed to unravel how microglia aggravate retinal degeneration due to deficiency in the engulfment receptor MerTK." (PMID 32765507, 2020). "Mutations in other genes expressed solely in the RPE, such as LRAT and MERTK, have been identified in patients with early-onset retinal degeneration, and mice carrying knockout (KO) mutations of these genes have the same effect." (PMID 31659211, 2019). "In fact, elimination of MerTK phosphorylation causes adult onset retinal degeneration through accum- ulation of debris and subsequent innate immunity inducement." (PMID 32489947, 2019). "The RCS rat bears a mutation of a RPE specific protein: MERTK, which is a tyrosine-protein kinase MER that has been also found in humans with early onset retinal degeneration and Leber Congenital Amaurosis." (PMID 28321183, 2017). "In one consanguineous family with MERTK-associated RP, the disease progressed more slowly, suggesting that genetic modifiers of MERTK-associated retinal degeneration exist in the human population." (PMID 26656104, 2015). "Previous MERTK-related retinal degenerations have been associated with recessive loss-of-function mutations." (PMID 25517981, 2014). "In addition, inhibition of microglial cells has been associated with a delay in the development of MerTK-associated retinal degeneration." (PMID 38680449, 2024). "Similarly, mutations in MERTK lead to retinitis pigmentosa type 38 (RP38) in humans causing early onset retinal degeneration and blindness." (PMID 32160519, 2020). "The role of MERTK loss-of-function in inherited retinal degeneration suggests that key signaling partners may be candidates for involvement in this group of diseases." (PMID 23390493, 2013).
retinal degeneration (continued). "The similarity in phenotypes between the two rodent models also suggests that the RPE phagocytic defect could contribute to retinal degeneration caused by the loss of function of MerTK in those rodents and perhaps in humans with MerTK defects." (PMID 22977300, 2012). "In addition to abolishing phagocytosis, MerTK deficiency in the eye also elicits harmful retinal inflammation, which can be alleviated with the application of anti-inflammatory drugs such as eye drops, which slow retinal degeneration in vivo." (PMID 34440696, 2021). "The role of MERTK in RPE-mediated phagocytosis for retinal homeostasis and the loss of function of this protein resulting in retinal degeneration were consolidated with the recapitulation of the RCS-like phenotype in mice genetically ablated for Mertk." (PMID 38791338, 2024). "Recent advancements in genetic analyses have revealed that mutations in some genes that are expressed in RPE, such as MERTK, RPE65, LRAT, or BEST1, cause retinal degeneration." (PMID 35504937, 2022). "One of the potential concerns for using MERTK inhibitors in the clinic is the on-target adverse event of rapid retinal degeneration." (PMID 35969037, 2022). "RCS rats in which a natural mutation of the MerTK receptor gene leads to an inactive truncated MerTK protein are well characterized for a defect of phagocytosis leading to retinal degeneration." (PMID 34829984, 2021). "RCS rat models, which are natural mutants for MerTK (RCS) vs. wild type rats (WT), were previously used mainly for studying the effects of MerTK on retina degeneration linked to a defect in photoreceptor outer segment phagocytosis." (PMID 34829984, 2021). "MERTK mutations are known to cause an RPE phagocytosis defect in animal models, leading to accumulation of POS in the IPM, and retinal degeneration and vision loss in RP 38 patients." (PMID 32160519, 2020). "The phagocytic defect in the RCS rat is due to a genetic defect in the major phagocytic receptor, MerTK, and this defect results in retinal degeneration in the rat." (PMID 29534722, 2018). "When we evaluated the visual cycle (a function unique to RPE), we observed that MerTK expression impacted the visual cycle prior to the onset of retinal degeneration." (PMID 29116131, 2017). "Mutations in several RPE-specific genes, including RPE65, LRAT (lecithin retinol acyltransferase) and MERTK (tyrosine-protein kinase Mer), have been identified in patients with early-onset retinal degeneration and LCA." (PMID 25650393, 2015). "Due to the role MERTK plays in clearance of apoptosis in the retina, MERTK inhibition could therefore lead to retinal degeneration and visual impairment." (PMID 39062902, 2024). "Therefore, early-onset, severe retinal degeneration was described to be a direct consequence of failed MERTK-mediated phagocytosis of photoreceptor outer segments by retinal pigment epithelia." (PMID 35969037, 2022). "Altogether, lack of galectin-3 causes overactivation primarily of Müller glia and worsens retinal injury, and this is not specific to retinal degeneration due to loss of the galectin-3 receptor MERTK." (PMID 35711472, 2022). "In animalmodels, MerTK deficiency and lack of engulfment cause dramatic, fast, andcomplete retinal degeneration." (PMID 33567017, 2021). "In degenerative RCS rat retinas (mutation of MERTK), increased pro-inflammatory cytokines and activation of microglia were detected starting from early stages of retinal degeneration, supporting the role of MERTK in the regulation of the TLR-mediated inflammatory response." (PMID 34207717, 2021). "In IRDs, retinal degeneration is caused by mutations in either genes expressed in photoreceptors or genes expressed in the adjacent RPE, as it is the case with mutations in RPE65, MERTK or LRAT." (PMID 30970664, 2019). "Finally, our results indicate that microglia driven processes aggravate retinal degeneration due to MerTK deficiency rather than playing a protective role." (PMID 32765507, 2020).
retinal degeneration (continued). "Since a slow form of retinal degeneration did indeed occur in Mertknmf12 or H716R and MERTK expression was not entirely abolished, potential problems with Mertk-/-V1 mice were not immediately brought to the fore." (PMID 35969037, 2022). "Acute re-expression of MerTK significantly but not completely decreases the severity of RCS rat retinal degeneration." (PMID 32765507, 2020). "Moreover, DKO mice lacking both galectin-3 and MERTK show significantly more pronounced Müller glia activation and retinal degeneration compared to mice lacking MERTK alone." (PMID 35711472, 2022). "We conclude that loss of the phagocytosis receptor MerTK causes microglia activation and relocalization in the retina before lack of RPE phagocytosis causes overt retinal degeneration, and that microglia activities accelerate loss of photoreceptors in mutMerTK-RP." (PMID 32765507, 2020). "The biological basis for the differences in retinal degeneration phenotype in the Mertk-/-V1 versus Mertk-/-V2 and Mertk-/-V3 mouse lines can also be trivially explained by a redundancy in phagocytosis provided for by TYRO3 in the absence of MERTK." (PMID 35969037, 2022). "For example, retinal degeneration seen in these mice, which had been previously ascribed to failure of MERTK-mediated phagocytosis of photoreceptor outer segments, is only present when TYRO3 function is also lost and was not seen in independently generated MERTK knockout mice." (PMID 37958886, 2023).
breast carcinoma (28 papers, 2013 to 2025). "Here are some instances of MERTK dysregulation in different cancers, like increased expression of MERTK has been associated with breast cancer progression." (PMID 41166341, 2025). "A previous study showed that the loss of MERTK in the tumor microenvironment of MERTK knockout mice slowed the establishment, growth, and metastasis of mammary tumors." (PMID 33562150, 2021). "However, across all subtypes of breast cancer, there is a significant loss of H3K27me3 modification, coinciding with the upregulation of MERTK in most subtypes." (PMID 38213995, 2024). "Another notable case is MERTK gene, which is known as an oncogene that promotes breast cancer progression." (PMID 38213995, 2024). "In breast disease, MerTK is expressed significantly higher in breast adenocarcinoma but lower in breast carcinoma." (PMID 38341954, 2024). "MERTK contributed to osteoblast dysfunction in osteolytic bone disease induced by breast cancer cells, whereas TYRO3 was bone-protective by promoting osteoblastogenesis and bone formation." (PMID 38203403, 2023). "We utilized a syngeneic mouse model of bone metastasis by using the EO771 breast cancer cell line in mice harboring a conditional deletion of MERTK and TYRO3 in osteoblasts (Col1a1-2,3kb-cre+Mertkflox/flox and Col1a1-2,3kb-cre+Tyro3flox/flox)." (PMID 38203403, 2023). "Based on the use of Mertk-/-V1 mice, it was also surmised that inhibition of macrophage efferocytosis due to MERTK loss of function results in decreased tumor growth and increased tumor-free survival (TFS) in E0771 murine breast cancer model." (PMID 35969037, 2022). "In this line, another recent study demonstrated MerTK’s tumor-promoting role in breast cancer, as its ablation increased tumor-related inflammation, therefore potentiating effects of PD-1 treatment resulting in tumor regression." (PMID 34771611, 2021). "Furthermore, in the EO771 breast cancer model, the combination of MerTK ASO and anti-PD1 resulted in significantly better tumor control compared to monotherapies." (PMID 38443968, 2024). "BT474, a HER2-positive breast cancer cell line, was also positive for MerTK expression." (PMID 38791148, 2024). "Indeed, the removal of apoptotic cells by MERTK-expressing macrophages induced an anti-inflammatory phenotype and promoted metastasis in breast cancer." (PMID 38573347, 2024). "An additional study showed that blocking MERTK might also influence osteoclastic bone resorption in breast cancer bone metastasis." (PMID 38203403, 2023). "Studies showed that PS-induced MerTK activation led to PD-L1 up-regulation in breast cancer cells." (PMID 33139930, 2021). "However, miR-126 targeting MerTK suppresses breast cancer metastasis through reduced endothelial cell recruitment." (PMID 34771611, 2021). "MerTK is an essential receptor for efferocytosis, a process that has been demonstrated to promote an immunosuppressive environment allowing tumor growth and metastasis in in vivo models of breast cancer." (PMID 33101282, 2020). "On the other hand, among breast cancer, we found seven out of eight invasive ductal carcinomas and four out of eight invasive lobular carcinomas presenting a positive staining for MerTK in immune infiltrate." (PMID 33101282, 2020). "Since miR‐335 was shown to be down‐regulated in aggressive CRC and breast cancer, one could speculate that aberrant expression of MERTK in CRC may be due to down‐regulation of miR‐335." (PMID 29101300, 2017). "In this regard, it is interesting that MerTK is highly expressed in breast adenocarcinoma but lowly expressed in common breast carcinoma, implying that the beneficial versus detrimental functions of MerTK mediated by efferocytosis may be cancer subtype-specific in impact." (PMID 38341954, 2024).
breast carcinoma (continued). "MerTK genetic ablation or inhibition by small molecules in leukocytes decreases tumor growth and enhances anti-tumor immune response by switching myeloid cell cytokine production from an immunosuppressive to an inflammatory state in an immunocompetent mouse model of breast cancer." (PMID 33101282, 2020). "BMS-777607 is currently undergoing phase II clinical trials for a number of different cancers, including breast cancer, and has activity against MET (IC50 3.9 nM), MERTK (IC50 14 nM) and NTRK1 (IC50 290 nM)." (PMID 30898150, 2019). "Furthermore, we demonstrated that MERTK and TYRO3 play a role in the development of osteolytic lesions in preclinical models of breast cancer metastasis." (PMID 38203403, 2023). "By using the syngeneic EO771 breast cancer bone metastasis model, we observed increased bone volume and reduced osteoclast numbers in bones of those animals in which MERTK was not expressed in the myeloid lineage (LysM-cre+Mertkflox/flox)." (PMID 38203403, 2023). "In co-culture studies with the breast cancer cell line MDA-MB.231, which expresses high levels of MerTK, we could show that low concentrations of Pros1 resulted in an enhanced inhibition of T cell activation by the cancer cells." (PMID 33801886, 2021). "PTPRN2, MERTK, TNC and SOX4 were identified to be targets of miR-335, AIB1 and CCND1 were the targets of miR-17-5p, and H-RAS and HMGA2 were verified as targets of let-7 in breast cancer." (PMID 30309377, 2018). "Pre-clinical studies using the MerTK inhibitor BMS-777607, a small molecule inhibitor that also targets the RTKs Met, Ron, Tyro3, and Axl, confirmed that efferocytosis can be blocked within highly apoptotic post-lactational mammary tumors." (PMID 30187085, 2018). "Interestingly, MerTK-/- leukocytes reduced tumor growth and expressed lower levels of anti-inflammatory cytokines such as IL-10, but higher levels of pro-inflammatory IL-6 and IL1-β in mammary cancer cells." (PMID 34771611, 2021). "Also overexpression of MERTK in non-tumorigenic breast cancer epithelial cells did not change proliferation." (PMID 27081701, 2016). "In the MMTV PyVmT mouse model of breast cancer, an increase in tumor cell death is seen in the absence of MerTK which is most likely due to inefficient efferocytosis as the tumor cells do not express appreciable levels of MerTK themselves." (PMID 26674639, 2015). "In breast cancer, the role of miR-126 in tumor metastasis may be related to the negative regulation of insulin receptor substrate-1 expression and it inhibits endothelial cell recruitment and angiogenesis through the negative regulation of IGFBP2/IGF1/IGF1R and GAS6/ MERTK signaling pathways." (PMID 24350576, 2013).
glioblastoma (26 papers, 2014 to 2025). The most malignant astrocytic tumor (WHO grade IV). "The two TAM receptors that are predominant in glioblastoma-associated macrophages are MERTK and AXL." (PMID 40610434, 2025). "To show the versatility of our gene-editing platform, we edited the CD14, CD47, TREM2, SIRPA and MERTK genes implicated in the clearance of Aβ and glioblastoma cells." (PMID 37483607, 2023). "S49076, a multi-kinase MET, AXL, and MERTK inhibitor, in combination with bevacizumab was also well tolerated in glioblastoma patients (ISRCTN11619481) in phase I/II study." (PMID 39062902, 2024). "In particular, MERTK, which is expressed in distinct types of cancer, including glioblastoma, showed high expression in two out of the three GS-derived SLGC lines and three GBM-derived lines." (PMID 38306361, 2024). "MERTK was upregulated in glioblastoma multiforme (GBM) stem-like cells and silencing of MERTK suppressed the self-renewal of patient-derived GBM stem-like cells." (PMID 34830794, 2021). "In contrast to our results MERTK knockdown in glioblastoma cells decreased migration but increased FAK and RhoA expression." (PMID 27081701, 2016). "With this study, we establish for the first time that Foretinib inhibits all of the TAM family members, and has highest potency against MerTK in the glioblastoma cells studied." (PMID 24658326, 2014). "Aberrant expression of Axl and MerTK has been described in multiple cancers, including glioblastoma, and in some cases Axl or MerTK overexpression or co-expression has been correlated with poor clinical outcomes." (PMID 24658326, 2014). "MerTK targeted shRNA completely prevented intracranial and subcutaneous glioma growth further delineating the impact of MerTK inhibition on glioblastoma." (PMID 24658326, 2014). "Inhibition of MerTK was found to greatly reduce glioblastoma migration and alter cellular morphology." (PMID 24658326, 2014). "From this we conclude that activation of TAM family members, and specifically MerTK, are successfully blocked in glioblastoma at concentrations lower than 1mM." (PMID 24658326, 2014). "Foretinib, an RTK inhibitor that targets TAM family members, with highest efficacy towards MerTK, effectively inhibited proliferation, survival, migration and invasion of human glioblastoma cells in vitro by blocking phosphorylation of the TAM kinase motif." (PMID 24658326, 2014). "A previous study on glioblastoma showed that knockdown of MerTK disrupted the rounded morphology of glioma cells with a decrease in tumor stem cell markers, such as Sox2 and Nestin, indicating that MerTK could maintain cells in an undifferentiated state." (PMID 38545840, 2024). "MERTK overexpression has also been observed in glioblastoma multiforme (GBM)." (PMID 39062902, 2024). "The ability of foretinib to inhibit the TAM family members of receptor tyrosine kinases (Tyro3, Axl, and MerTK) hindered the survival, proliferation, and migration of glioblastoma cell lines in vitro and reduced glioblastoma tumor growth in a subcutaneous mouse model." (PMID 35743016, 2022). "Inhibition of MERTK leads to cellular senescence in glioblastoma cells." (PMID 33964983, 2021). "In conclusion, we have shown that MerTK is essential for glioblastoma growth." (PMID 24658326, 2014). "We now demonstrate for the first time that the tyrosine kinase inhibitor Foretinib effectively inhibits TAM family members in glioblastoma, and most robustly MerTK, leading to an inhibition of the critical phenotypes of glioblastoma and a dramatic tumor response in in vivo mouse models of disease." (PMID 24658326, 2014). "To illustrate the importance of MerTK in glioblastoma growth we developed genetically inhibited cell lines to use in in vivo modeling; U251 cells were transduced with shMerTK and sorted based on expression levels of MerTK following puromycin selection." (PMID 24658326, 2014).